CAV1 (caveolin 1)
Diseases named in the same sentence as CAV1 in open-access papers (continued):
Sharing a sentence is not in itself a finding about the gene and the disease.
Alzheimer disease (26 papers, 2008 to 2025). A progressive, neurodegenerative disease characterized by loss of function and death of nerve cells in several areas of the brain leading to loss of cognitive function such as memory and language. "For example, functional Cav-1 plays a role in HIV-related accumulation of amyloid-β, while Cav-1 deficient mice develop a pathological phenotype similar to that of Alzheimer's disease." (PMID 23060817, 2012). "As with the gene profiles of Cav-1 (-/-) stromalcells, the Alzheimer's disease profiles were most significantly associated with the "metastasis-prone" stromal geneset (p = 9 x 10-5)." (PMID 20442453, 2010). "It is unknown whether loss of synapses is dependent on an age-related loss of Cav-1 expression and whether this has implications for neurodegenerative diseases such as Alzheimer's disease." (PMID 21203469, 2010). "Elevated levels of Cav-1 in neurons boost synaptic signaling and plasticity, resulting in improved memory and cognitive abilities in Alzheimer’s disease models." (PMID 40358155, 2025). "While the ablation of Cav1 leads to molecular and cellular changes in mice that are the hallmarks of Alzheimer’s disease, the role of Aplp2 in neurodegeneration in mice is not known." (PMID 38334607, 2024). "Cav-1 therapy has also been shown to preserve or delay neurodegeneration in a preclinical model of Alzheimer's disease." (PMID 36760400, 2023). "Cav1 expression is increased in several neurodegenerative diseases, including Alzheimer’s disease (AD), suggesting Cav1 as a potential therapeutic target." (PMID 36854997, 2023). "In addition, Cav-1 in astrocytes is associated with reactivity, with SorLA, a protein with sorting and trafficking functions and demonstrated relevance to Alzheimer’s disease, with expression of connexin Cx43, and with fatty acid-binding proteins (FABPs)-related signals." (PMID 29163047, 2017). "Increases in caveolin-1 levels have been reported in Alzheimer’s disease previously, supporting a potential role of caveolin-1 in ADDL toxicity." (PMID 27639375, 2016). "We furthermore find that the increase in IR/caveolin-1 interactions in our Alzheimer’s disease models in vitro and in vivo is reduced upon GCS inhibition." (PMID 27639375, 2016). "Aging increases the likelihood of dementia and Alzheimer's disease, and localization of synaptic signaling components in neuronal MLRs is reduced in brains from aged WT and young Cav-1 KO mice." (PMID 23060817, 2012). "The role of caveolin-1 in the CNS in the context of neuronal plasticity and Alzheimer's disease is well known, and neurological abnormalities have been reported in caveolin-1 knock-out mice." (PMID 24961257, 2012). "Elevated levels of CAV-1 and CAV-2 have been associated with several forms of cancer, Alzheimer disease, and other human diseases." (PMID 22128235, 2011). "We have previously shown that the transcriptional profiles of Cav-1 (-/-) stromalcells significantly ovelap with the transcriptional profiles obtained from theanalysis of Alzheimers disease brain." (PMID 20442453, 2010). "A study performed by other researchers has shown that Cav1-knockout (KO) in mice leads to increased amyloid beta, hyperphosphorylation of tau, astrogliosis and the decreased cerebrovascular volume of the brain which are hallmarks of Alzheimer’s disease." (PMID 38334607, 2024). "Cav1-null mice show Alzheimer’s disease (AD)-like symptoms at an early adult life." (PMID 38790233, 2024). "In addition, in the caveolin-1 knockout mice, the neurological abnormalities, as seen in Alzheimer’s disease, were noted." (PMID 35628311, 2022). "In order to reveal a potential mechanism as to how membrane microdomains containing gangliosides may regulate surface IR in Alzheimer’s disease, we studied the process of IR endocytosis involving caveolin-1." (PMID 27639375, 2016).
Alzheimer disease (continued). "Interestingly, in post-mortem samples of human hippocampus and cortex in patients with Alzheimer's disease, cytospatial distribution of Cav-1 and the voltage-dependent anion channel (VDAC) is increased." (PMID 23060817, 2012). "In contrast, the absence of Cav-1 results in accelerated neuronal aging, heightened accumulation of Aβ and phosphorylated Tau, and a decrease in hippocampal synapses, resembling the pathology associated with Alzheimer’s disease." (PMID 40358155, 2025). "Furthermore, the assumption that gangliosides may facilitate complex formation between IR and caveolin-1 in Alzheimer’s disease was also corroborated in vivo." (PMID 27639375, 2016). "Not only Cav1, but also the ubiquitously expressed ITSN-1s, a major protein of lung tissue, has been related to lung inflammatory conditions, to endosomal disorders associated with the earliest pathogenesis of Alzheimer's disease and Parkinson's diseases as well as cancer." (PMID 22506115, 2012). "Therefore, Cav-1 represents a novel control point for healthy neuronal aging and loss of Cav-1 represents a non-mutational model for Alzheimer's disease." (PMID 21203469, 2010). "Neuron-targeted Cav-1 re-expression/over-expression offers the novel possibility of re-establishing the fidelity of neuroprotective signaling that is lost with advanced age or in other forms of neurodegeneration (i.e., dementia, Alzheimer's disease, depression, Parkinson's disease)." (PMID 21203469, 2010). "Caveolin-1 may play a role in non-genomic steroid receptor mediated effects and has been implicated in several types of cancer, metabolic, and cardiovascular disease, and via its link with cholesterol transport in Alzheimer's disease." (PMID 20098621, 2010).
ischemic stroke (26 papers, 2016 to 2025). A stroke disorder caused by obstruction of blood flow to the brain, due to thrombotic (local blood clot formation) or embolic (due to a blood clot or other material traveling from another site) event. "In an ischemic stroke mouse model, Cav-1 deficiency correlated with the increase in the degradation of TJs and the hydrolytic activity of matrix metalloproteinases, thereby enhancing BBB permeability." (PMID 36741925, 2023). "In the present study, whether circulating Cav‐1 level could predict the risk of sICH in a cohort of ischaemic stroke patients receiving EVT treatment was investigated." (PMID 38757755, 2024). "Several receptors associated with Cav-1 and MLRs are crucial to neuroplasticity, and may be potential therapeutic targets to improve functional recovery after ischemic stroke." (PMID 31673241, 2019). "However, the relationship between genotypic polymorphisms of e-NOS and Cav-1 genes and ischemic stroke (IS) remains lesser reported." (PMID 28346478, 2017). "Therefore, in this study, we investigated the association between serum Cav-1 levels and cSVD detected and measured with MRI in a cohort of patients with ischemic stroke." (PMID 27119011, 2016). "Altogether, our study demonstrates the novel mechanism of Cav-1-dependent tight-junction proteins autophagic disruption on BBB integrity after ischemic stroke, and BMSC-sEVs treatment can reverse such hazard cascades." (PMID 39781452, 2025). "In contrast, Cav‐1 negatively regulates neurogenesis following a stroke, with its downregulation facilitating neuronal differentiation in ischemic stroke, potentially improving clinical outcomes." (PMID 40778471, 2025). "The second most cited article titled “Matrix metalloproteinase-2-mediated occludin degradation and caveolin-1-mediated claudin-5 redistribution contribute to BBB damage in the early stage of ischemic stroke” was published in The Journal of Neuroscience." (PMID 39119484, 2024). "After ischemic stroke, cortical neuronal death, and hypoxia-induced astrocyte apoptosis, Cav-1, through the Ras/Ras/ERK signaling pathway, protects against hypoxia-induced astrocyte apoptosis." (PMID 38922036, 2024). "Our purpose was to assess the role of circulating Cav‐1 levels in predicting symptomatic intracranial haemorrhage (sICH) amongst ischaemic stroke patients after endovascular thrombectomy (EVT)." (PMID 38757755, 2024). "Schematic diagram of the promotion of miR‐199a‐5p on endogenous neurogenesis via inhibiting of Cav‐1 signaling pathway during the recovery after ischemic stroke." (PMID 37349971, 2023). "Studies from mouse ischemic stroke model demonstrated that Cav-1 immunoreactivity is significantly and specifically increased in the endothelial cells in the infarcted area 24 h post-MCA occlusion (MCAO)." (PMID 35557625, 2022). "Cav1-KO mice showed less laminin-labeled endothelial cells in the ipsilateral hemisphere following ischemic stroke than WT mice." (PMID 32523952, 2020). "This review will highlight the role of Cav-1 and MLRs in neuronal growth following ischemic stroke, with an emphasis on the mechanisms by which Cav-1/MLRs modulate neuroplasticity via related receptors, signaling pathways, and genes." (PMID 31673241, 2019). "This review addresses the role of Cav-1 and MLRs in neuronal growth after ischemic stroke, with an emphasis on the mechanisms by which Cav-1/MLRs modulate neuroplasticity via related receptors, signaling pathways, and gene expression." (PMID 31673241, 2019). "In conclusion, cav-1 promotes neurogenesis and neuroplasticity after ischemic stroke, but some studies demonstrate that cav-1 inhibits neural progenitor cells differentiation under normoxic and hypoxic conditions through the downregulation of VEGF signaling." (PMID 30572925, 2018).
ischemic stroke (continued). "This article reviews recent developments in understanding the mechanisms underlying BBB dysfunction, neuroinflammation, and oxidative stress after ischemic stroke, and focuses on how cav-1 modulates a series of activities after ischemic stroke." (PMID 30572925, 2018). "Most importantly, Cav-1 OE ameliorated the vasogenic edema through the inhibition of TJ protein degradation in the acute phase of ischemic stroke." (PMID 27708218, 2016). "The average fluorescence intensity (FI) in the acute phase of ischemic stroke was significantly lower in the Cav-1 OE rats compared to that in the control group (P < 0.01)." (PMID 27708218, 2016). "Cav-1 knockout (KO) ischemic stroke models exhibited increased BBB permeability, redox imbalance, and amplified proinflammatory cytokines." (PMID 27119011, 2016). "Caveolin‐1 (Cav‐1) is reported to mediate blood–brain barrier integrity after ischaemic stroke." (PMID 38757755, 2024). "Our previous study confirmed that reduced Cav‐1 was associated with poor functional outcomes at 3 months in ischaemic stroke patients after EVT, amongst which existed a negative linear dose–response association." (PMID 38757755, 2024). "In this study, it is aimed to identify whether miR‐199a‐5p/Cav‐1 pathway by enhancing endogenous neurogenesis promotes functional recovery after ischemic stroke." (PMID 37349971, 2023). "In addition, Cav-1 deficiency leads to decreased AQP4 expression and impaired perivascular AQP4 coverage after ischemic stroke." (PMID 35873558, 2022). "Mice with caveolin-1 knockout had less lesions, lower neurological deficits, and less cerebral edema after intracerebral hemorrhage but caveolin-1 knockout mice showed a high level of apoptotic death of penumbra cells after ischemic stroke." (PMID 36289917, 2022). "Other agents may also target Cav-1 to enhance neuronal growth and neuroplasticity following ischemic stroke." (PMID 31673241, 2019). "We further discuss how Cav-1/MLRs may be exploited as a potential therapeutic target to restore neuroplasticity after ischemic stroke." (PMID 31673241, 2019). "Based on these findings, modulation of Src and Cav-1 may provide a novel approach to promote neuronal growth after ischemic stroke." (PMID 31673241, 2019). "Taken together, cav-1 inhibits MMP-9 under ischemic stroke condition." (PMID 30572925, 2018). "The following discussion is about the role of cav-1 in ischemic stroke." (PMID 30572925, 2018). "Importantly, Cav-1 OE ameliorated the vasogenic edema by inhibiting the degradation of TJ protein expression in the acute phase of ischemic stroke." (PMID 27708218, 2016). "Cav-1 may promote angiogenesis and collateralization in ischemic stroke and limb ischemia." (PMID 35557625, 2022). "Caveolin-1 may be a key factor in maintenance of MLRs and neuroplasticity after ischemic stroke." (PMID 31673241, 2019). "Thus, miR-199a may act as a negative regulator of Cav-1 in neuroplasticity following ischemic stroke." (PMID 31673241, 2019). "Thus, cav-1 could be a novel therapeutic target protein for promoting neurogenesis after ischemic stroke." (PMID 30572925, 2018). "In the present study, we found that the down‐regulation of Cav‐1 following the treatment of miR‐199a‐5p agomir was accompanied by the increased expression of VEGF and BDNF after ischemic stroke in rats." (PMID 37349971, 2023). "Thus, Cav-1 may act through TrkB to promote nerve regeneration after ischemic stroke." (PMID 31673241, 2019). "Our results show that the expression of caveolin-1 and HG-CD147 was upregulated in DM rats with ischemic stroke." (PMID 30953513, 2019). "By employing different phase autophagy regulators and Cav-1 siRNA and pcDNA3.1 plasmid, we verified that the therapeutic efficacy of BMSC-sEVs on BBB integrity was Caveolin-1-dependent autophagic degradation of ZO-1 and Occludin after ischemic stroke." (PMID 39781452, 2025).
ischemic stroke (continued). "Their protective role in ischemic stroke is not necessarily due to the reduction of cav-1, and there is no further intervention on cav-1." (PMID 30572925, 2018). "In general, cav-1 can increase BBB permeability through caveolae-mediated endocytosis and translocation of TJ protein, but can also protect BBB integrity by inhibiting MMP activity during ischemic stroke." (PMID 30572925, 2018). "Thus, Rab7a EC-specific deletion did not affect the acute transcellular BBB leakage after ischemic stroke or the upregulation of Cav-1 protein." (PMID 41024170, 2025). "The present study revealed that Caveolin-1, alone with p-Src, increased in ischemic stroke mouse brain tissue upon delayed treatment with tPA, consistent with the result from others, which was abrogated by addition of QSYQ, suggesting Src/Caveolin-1 as one of the targets for QSYQ to act." (PMID 35095486, 2021). "Thus, the purpose of the present study was to investigate if the overexpression (OE) of Cav-1 affected BBB disruption or vasogenic brain edema following MCAO and if Cav-1 prevented TJ protein degradation at the most critical period of vasogenic cerebral edema in the acute phase of ischemic stroke." (PMID 27708218, 2016). "The results illustrated that the major transcellular proteins, Cav-1, Mfsd2a, and AQP4, have been changed and led to increasing transcellular permeability at the early stage of ischemic stroke, while the TJ proteins are not significantly altered or dysregulated." (PMID 35873558, 2022).
bladder cancer (24 papers, 2007 to 2025). "Analysis of 53 high-grade bladder carcinomas associated with metastases and also provisional TCGA RNA sequencing data suggests a strong association between high CAV1 expression and reduced survival." (PMID 35326708, 2022). "Functional studies suggested that mTORC2 could utilize Cav-1 regulation to secondarily impact the expression and/or stability of caveolar-associated receptor tyrosine kinases (RTKs) important for bladder cancer growth." (PMID 35326708, 2022). "In addition, high expression of Cav-1 and low expression of Src were associated with metastasis and poor survival in bladder cancer and suggested that these both control bladder metastases through the Rho–ROCK pathway." (PMID 22353809, 2012). "Urinary tract tumors, including prostate but also kidney and bladder cancers, show increased levels of cav-1." (PMID 39857963, 2025). "GATA-3 and Caveolin-1 have been demonstrated as potential biomarkers of the biological behavior of canine bladder carcinoma, correlating with MC." (PMID 36299636, 2022). "But one study has found that compared with normal tissue, CAV1 had a decreased expression in bladder cancer tissues." (PMID 29190968, 2017). "The positive expression of CAV1 was more observed in high grade urothelial carcinoma and bladder cancer patients." (PMID 29190968, 2017). "Previous studies have shown that activation of Cav-1 induces epithelial-to-mesenchymal transition of bladder cancer cells through upregulation of Slug expression, which occurs through activation of the PI3K/AKT signaling pathway." (PMID 26919102, 2016). "MiR-133a targets FSCN1 in bladder cancer and CAV1 in head and neck squamous cell carcinoma functioning as a tumor suppressor." (PMID 25104873, 2014). "The aim of this current study was to assess the expression and activity of Src family kinases, focal adhesion kinase (FAK), caveolin (Cav-1) and RhoGD12 in bladder cancer." (PMID 22353809, 2012). "In bladder cancer, it has previously been reported that Cav-1 expression is elevated at the onset of oncogenesis and these levels rise further with progression of the disease in terms of stage and grade." (PMID 22353809, 2012). "Recent studies revealed that the caveolin-1 promoter region is hypermethylated in lung, breast, cervical and bladder cancers, as well as leukemia." (PMID 22894556, 2012). "For example, NIH3T3 cells treated with anti-sense caveolin-1 were resistant to staurosporine-induced apoptosis, and T24 bladder carcinoma cells were sensitized to caspase 3 activation when stably expressing recombinant caveolin-1." (PMID 17331262, 2007). "Although there have been reports on the association of DNM2 and CAV1 expressions with cancer cell biology in bladder cancer, to our knowledge there has been no investigation into the significance of the expression profiles of DNM2 and CAV1 in OSCC." (PMID 40419438, 2025). "Interestingly, our own study demonstrated a unique role for mTORC2-mediated regulation of caveolae formation through Cav-1 expression in actively migrating bladder cancer cells." (PMID 35326708, 2022). "Previous work has shown that Cav-1 and Src have a reciprocal relationship in bladder cancer." (PMID 22353809, 2012). "In molecular studies, miR-133a has been shown to directly regulate several metastasis-related oncogenes, including FSCN1 in bladder cancer, LASP1 in CRC, and CAV1 in head and neck squamous cell carcinoma." (PMID 25104873, 2014). "Ectopic expression of caveolin-1 in NIH3T3 cells and T24 human bladder carcinoma cells sensitizes cells to staurosporine-induced apoptosis." (PMID 17331262, 2007). "Cytotoxicity is assessed and the expression of Toll‐like receptor 4 (TLR4) and caveolin‐1 (CAV‐1), in the presence or absence of simulated infection with bacterial lipopolysaccharide (LPS), is evaluated using the human urinary bladder cancer cell line T24." (PMID 38554019, 2024).